TMOD1 (tropomodulin 1)
Description:
Blocks the elongation and depolymerization of the actin filaments at the pointed end. The Tmod/TM complex contributes to the formation of the short actin protofilament, which in turn defines the geometry of the membrane skeleton. May play an important role in regulating the organization of actin filaments by preferentially binding to a specific tropomyosin isoform at its N-terminus.
Synonyms: D9S57E; TMOD; ETMOD
Tractability: Small molecule: a structure with a bound ligand is known. PROTAC: its protein half-life has been measured.
Gene: Protein-coding gene on chromosome 9 (97,501,180 to 97,601,743, forward strand). Ensembl gene ENSG00000136842.
Subcellular location: Cytoplasm, cytoskeleton
Pathways (Reactome):
Muscle contraction: Striated Muscle Contraction
Gene Ontology:
Molecular function: actin binding; tropomyosin binding
Biological process: actin filament organization; muscle contraction; myofibril assembly; lens fiber cell development; pointed-end actin filament capping
Cellular component: actin filament; COP9 signalosome; myofibril; sarcomere; striated muscle thin filament; cytoskeleton; cytosol; cortical cytoskeleton; membrane
Genetic constraint (gnomAD): Loss-of-function variants: 16 observed, 40.89 expected, observed/expected ratio (o/e) 0.39, 90% interval 0.26 to 0.59. The upper end of that interval is the gene's LOEUF score, 0.59, which puts it in group 2 of 6, group 1 being the genes least tolerant of losing a copy. Missense variants: 391 observed, 463.11 expected, observed/expected ratio (o/e) 0.84, 90% interval 0.78 to 0.92. Synonymous variants: 179 observed, 181.44 expected, observed/expected ratio (o/e) 0.99, 90% interval 0.87 to 1.12.
Gene-disease validity (ClinGen):
ClinGen rates the evidence that TMOD1 causes each of these diseases.
dilated cardiomyopathy (autosomal recessive): Limited. Cardiomyopathy which is characterized by dilation and contractile dysfunction of the left and right ventricles.
Homologues: Orthologues: chimpanzee TMOD1 (99% identical), dog TMOD1 (98% identical), pig TMOD1 (97% identical), guinea pig TMOD1 (97% identical), mouse Tmod1 (97% identical), rat Tmod1 (97% identical), rabbit TMOD1 (96% identical), macaque TMOD1 (95% identical), tropical clawed frog tmod1 (79% identical), zebrafish tmod1 (77% identical), Caenorhabditis elegans unc-94 (38% identical), Drosophila melanogaster tmod (25% identical). Paralogues in human: TMOD3 (60% identical), TMOD2 (58% identical), TMOD4 (57% identical), LMOD2 (39% identical), LMOD1 (36% identical), LMOD3 (36% identical).
Diseases named in the same sentence as TMOD1 in open-access papers:
TMOD1 is named in the same sentence as 39 diseases in open-access papers, as found by Europe PMC text mining. Sharing a sentence is not in itself a finding about the gene and the disease. The quoted sentences say what the papers report.
cardiomyopathies (2 papers, 2021 to 2024). "While thin-filament gene defects are established causes of cardiomyopathies and nemaline myopathies, TMOD1, encoding a protein that localizes to the tip of the thin filament, is a new addition to this disease gene group." (PMID 38168645, 2024). "These pieces of evidence strongly suggest that the molecular mechanism underlying TMOD1 cardiomyopathy caused by the p.R189W variant is the dysregulation of thin filament lengths." (PMID 38168645, 2024). "Our data indicate that the p.R189W variant in TMOD1 has altered biochemical properties and reveals a unique mechanism for childhood-onset cardiomyopathy." (PMID 38168645, 2024). "Many other sarcomeric proteins have been previously linked to cardiomyopathies, including TPM1, an interacting partner of TMOD1." (PMID 38168645, 2024).
Huntington disease (2 papers, 2021 to 2022). Huntington disease (HD) is a rare neurodegenerative disorder of the central nervous system characterized by unwanted choreatic movements, behavioral and psychiatric disturbances and dementia. "We finally screened five genes, including Arpp21, Rgs4, Rasd2, Gabrd, and Tmod1, two (Arpp21 and Rasd2) of which have been reported to be related with Huntington’s disease." (PMID 34433483, 2021). "Tropomodulin 1 (TMOD1), an actin-binding protein essential for synapse formation, was found downregulated in the striatum of Huntington’s disease mice." (PMID 36523271, 2022).
neuroblastoma (2 papers, 2013 to 2018). Neuroblastoma (NB) is the most common solid, extracranial childhood tumor. "In vitro characterization and functional studies led us to better understand the role of TMOD1 in neuroblastoma cell lines." (PMID 29930753, 2018). "To further examine the TMOD1 functional role in neuroblastoma cells, we studied the effects of TMOD1 downregulation utilizing RNA interference technique." (PMID 29930753, 2018). "Functional studies on neuroblastoma cell lines, showed that TMOD1 knockin induced cell cycle arrest, cell proliferation arrest and a mature functional differentiation." (PMID 29930753, 2018). "In N2a neuroblastoma cells (model system to study neuritogenesis), both Tmod1 and Tmod2 were expressed, but levels of Tmod1 increased drastically starting 24 hours after induction of neuritogenesis." (PMID 23638401, 2013). "Cells differentiation was analyzed in both cell lines by immunocytochemistry and representative images by confocal microscopy showed that TMOD1 knockin induced neuroblastoma cells differentiation characterized by long neurites with sprouting, growth cones and varicosities." (PMID 29930753, 2018). "Our data clearly demonstrated extensively a positive and specific correlation between TMOD1 and TMOD2 expression levels and neuroblastoma; high expression levels of these two genes were associated with high survival probability and good prognosis of neuroblastoma patients’." (PMID 29930753, 2018). "We assessed the expression of TMOD1 and TMOD2 genes in 17 different datasets comprising different types of tumors and we added an additional neuroblastoma dataset as control." (PMID 29930753, 2018). "First, we evaluated the presence and the expression levels of TMOD1 and TMOD2 in SH-SY5Y and SK-N-SH neuroblastoma cells." (PMID 29930753, 2018). "TMOD1 and TMOD2 were highly expressed in neuroblastoma, relative to other tumor types, suggesting an important role of these genes in the tumor homeostasis." (PMID 29930753, 2018). "We found that TMODs expression varied among tumor types but the highest expression of TMOD1 and TMOD2 was observed in neuroblastoma tumors (Bonf p<0.01)." (PMID 29930753, 2018).
oral squamous cell carcinoma (2 papers, 2019 to 2025). "Evidences have shown that high expression of TMOD1 is a key prognostic marker for patients with oral squamous cell carcinoma and is closely associated with regional lymph node metastasis." (PMID 39744479, 2025). "Overexpression of TMOD1 promotes cell proliferation of breast cancers and metastasis of oral squamous cell carcinoma." (PMID 31333911, 2019).
adenovirus infection (1 paper, 2020). "We introduced exogenous Tmod1 into TOT/Tmod1-/- imDCs by adenovirus infection and then treated cells with LPS." (PMID 33552047, 2020).
anemia (1 paper, 2013). A reduction in the number of red blood cells, the amount of hemoglobin, and/or the volume of packed red blood cells. "For example, Tmod1-null mice exhibit anemia associated with increased osmotic fragility and reduced red blood cell deformability." (PMID 23424621, 2013).
autoimmune disease (1 paper, 2020). A disorder resulting from loss of function or tissue destruction of an organ or multiple organs, arising from humoral or cellular immune responses of the individual to their own tissue constituents. "Tmod1 may be a potential target for regulating DC functions in order to exaggerate or suppress the immune responses in the body, which would be beneficial to the immunotherapy for many diseases including cancer, transplant rejection, infection, and autoimmune diseases." (PMID 33552047, 2020).
cataract (1 paper, 2012). Partial or complete opacity of the crystalline lens of one or both eyes that decreases visual acuity and eventually results in blindness. "Visual inspection of 2-mo-old dissected lenses revealed no cataracts or gross anatomical abnormalities arising from the absence of Tmod1 and/or CP49, and no significant changes in lens axial and equatorial diameters, aspect ratios, or volumes were observed." (PMID 23144950, 2012).
dilated (1 paper, 2024). "Our evidence, including genetics, protein modeling, cultured cardiomyocytes, and biochemical data, indicate that to the best of our knowledge, TMOD1 is a novel disease gene underlying childhood-onset dilated and restrictive cardiomyopathy." (PMID 38168645, 2024). "Through exome sequencing, we report a homozygous variant in tropomodulin 1 (TMOD1; c.565C>T, p.R189W) in three individuals from two unrelated families with childhood-onset dilated and restrictive cardiomyopathy." (PMID 38168645, 2024).
dilated cardiomyopathy (1 paper, 2016). "Knockout mice of Tmod1 are embryonic lethal due to cardiac defects, and overexpression of Tmod1 in the heart causes myofibril disorganization and dilated cardiomyopathy (DCM)." (PMID 27274810, 2016).
experimental autoimmune encephalomyelitis (1 paper, 2020). An autoimmune demyelinating disease of the central nervous system that is produced experimentally in animals by the injection of homogenized brain or spinal cord in Freund's adjuvant. "Furthermore, Tmod1-deficient mDCs secreted high levels of IFN-β and IL-10 and induced immune tolerance in an experimental autoimmune encephalomyelitis (EAE) mouse model." (PMID 33552047, 2020). "Furthermore, LPS-treated Tmod1-deficient DCs secreted high levels of IFN-β and IL-10, and induced immune tolerance in an experimental autoimmune encephalomyelitis (EAE) mouse model." (PMID 33552047, 2020).
restrictive cardiomyopathy (1 paper, 2024). A type of heart disorder referring to the inability of the ventricles to fill with blood because the myocardium (heart muscle) stiffens and looses its flexibility. "This study reports the first homozygous TMOD1 pathogenic variant to our knowledge, p.R189W, as a cause of dilated and restrictive cardiomyopathy in three pediatric patients from two unrelated families." (PMID 38168645, 2024). "Genomic, cellular, and biochemical analyses reveal that the homozygous p.R189W variant in TMOD1 leads to dysregulation of thin filament lengths in the heart and causes childhood-onset dilated and restrictive cardiomyopathy in three patients." (PMID 38168645, 2024).
Skeletal myopathy (1 paper, 2024). "This is supported by our findings, indicating that partially dysfunctional TMOD1 causes childhood-onset cardiomyopathy without skeletal myopathy." (PMID 38168645, 2024).
T-Cell Lymphoma (1 paper, 2024). "A study from the European T-Cell Lymphoma Study Group identified a set of three genes (TNFRSF8, BATF3, and TMOD1) whose co-expression could potentially distinguish ALK-negative ALCL from PTCL-NOS, with an overall accuracy of approximately 97% in unrelated groups of patients." (PMID 38921179, 2024).
thyroid carcinoma (1 paper, 2022). "Taken together, we propose that TMOD1 polymorphisms may play a potential role in thyroid carcinoma." (PMID 36316666, 2022). "In this study, we assessed the association of the TMOD1 (rs1052270, rs10982622, and rs1475545) and PTCSC2 (rs16924016, rs925489, and rs965513) gene polymorphisms with susceptibility to thyroid carcinoma." (PMID 36316666, 2022). "The purpose of this study was to survey the associations of six single nucleotide polymorphisms (SNPs) in the TMOD1 and PTCSC2 genes with thyroid carcinoma (TC)." (PMID 36316666, 2022). "Studies of the mechanism between TMOD1 and PTCSC2 polymorphisms and thyroid carcinoma should be conducted to explore the effect." (PMID 36316666, 2022). "In conclusion, we found that TMOD1 and PTCSC2 were correlated with thyroid carcinoma risk in the Chinese Han population." (PMID 36316666, 2022). "In our results, we found that the association between the polymorphism of TMOD1 and PTCSC2 polymorphisms and thyroid carcinoma risk was affected by age and sex." (PMID 36316666, 2022). "TMOD1 polymorphism was detected to be markedly decreased, and PTCSC2 was detected to be markedly increased in thyroid carcinoma risk based on our analysis." (PMID 36316666, 2022). "The function of TMOD1 in thyroid carcinoma is still unknown, although we have known its role in several types of cancer." (PMID 36316666, 2022). "Due to ethnic and population differences, this study investigated whether six polymorphic loci of TMOD1 and PTCSC2 were related to the susceptibility of thyroid carcinoma to further reveal the genetic pathogenesis of thyroid diseases in the Chinese population." (PMID 36316666, 2022). "The genetic polymorphisms of TMOD1 may not be a key part of susceptibility to thyroid carcinoma." (PMID 36316666, 2022). "However, no study has focused on the association between TMOD1 polymorphisms and thyroid carcinoma." (PMID 36316666, 2022).
yellow fever (1 paper, 2020). "Interestingly, numerous SLC family genes are also significantly correlated with cell-mediated responses after yellow fever vaccination, although the only shared gene which was correlated with CD8 T-cell response in our study and after yellow fever vaccination was TMOD1." (PMID 33244316, 2020).
tumor (6 papers, 2017 to 2025). "Analysis of clinical data further revealed that high TMOD1 expression correlated with early pathological stages, while low TMOD1 levels associated with advanced disease, supporting its role as a potential tumor suppressor in CC." (PMID 41148856, 2025). "TMOD1 downregulation also induced cell proliferation arrest but caused the loss of mature cell differentiation and promoted the development of neuroendocrine cellular characteristics, delineating an aggressive and unfavorable tumor behavior." (PMID 29930753, 2018). "High expression of TMOD1 has been confirmed to correlate with tumor growth and enhanced lymph node metastasis." (PMID 40703522, 2025). "The data indicated that, in both cell lines, TMOD1 knockin blocked cells in G0/G1 phase decreasing the tumor cells number in proliferation." (PMID 29930753, 2018). "Additionally, IHC was performed to detect Ki67 positive cells to evaluate tumor proliferation, demonstrating that TMOD1 notably reversed the suppressive impact exerted by miR-MTCO3P38 on tumor proliferation." (PMID 39744479, 2025). "Thus, in our experimental data, TMOD1 knockdown induced high expression levels of all unfavorable neuroendocrine biomarkers, delineating an aggressive tumor profile." (PMID 29930753, 2018). "Tumor xenograft model mice were conducted, and in vivo assays further confirmed that miR-MTCO3P38 restrained tumor growth and proliferation in HCC by inhibiting the TMOD1/MMP13 pathway." (PMID 39744479, 2025). "The protein expression of TMOD1/MMP13 pathway and tumor invasion-related factors were detected by western blot, illustrating that overexpression of TMOD1 rescued the downregulation of TMOD1 and MMP13, which was caused by high expression of miR-MTCO3P38." (PMID 39744479, 2025). "NF-κB was shown to signal Tropomodulin 1 (TMOD1)-dependent β-catenin transactivation and MMP secretion in TNBC BCa cells leading to invasion and tumor growth." (PMID 35626710, 2022). "Afterwards, in vitro and in vivo experiments showed that overexpression of TMOD1 reversed the inhibitory effects of miR-MTCO3P38 on migration and invasion of HCC cells and tumor growth, illustrating that miR-MTCO3P38 restrained tumor growth and development by targeting TMOD1/MMP13 pathway." (PMID 39744479, 2025). "In terms of tumor invasion, overexpression of miR-MTCO3P38 significantly increased E-cadherin and Claudin-1 expression and reduced N-cadherin level, while overexpression of TMOD1 reversed the situation." (PMID 39744479, 2025). "In vivo, tumor growth was measured, and the impacts of miR-MTCO3P38 and its target gene on tumor pathology, proliferation, TMOD1/MMP13 pathway and tumor invasion-related factors were evaluated by hematoxylin-eosin staining, immunohistochemistry (Ki67) and western blot." (PMID 39744479, 2025). "Mice weight, the size, weight, and volume of tumors were measured, and the pathological changes of the tumor tissue were observed by HE staining, demonstrating that overexpression of miR-MTCO3P38 inhibited tumor growth and development in HCC mice, which was weakened by TMOD1 overexpression." (PMID 39744479, 2025).
cancer (3 papers, 2020 to 2022). A tumor composed of atypical neoplastic, often pleomorphic cells that invade other tissues. "Meanwhile, TMOD1 has an important role in the regulation of action dynamics in cancer development." (PMID 36316666, 2022). "Increasing evidence indicates that TMOD1 is related to several processes of cancer development." (PMID 36316666, 2022).
TMOD1 also shares sentences with these, for which no sentence is quoted: ovarian carcinoma (2 papers); Alzheimer disease (1); anaplastic large cell lymphoma (1); Arthritis (1); Barrett's oesophagus (1); brain disorder (1); breast carcinoma (1); cardiac hypertrophy (1); carnitine deficiency (1); colon cancer (1); congenital myopathies (1); coronary artery disease (1); endometriosis (1); hepatocellular carcinoma (1); infection (1); melanoma (1); meningioma (1); muscular dystrophies (1); oesophageal adenocarcinoma (1); pancreatic cancer (1); prostate carcinoma (1).